SPART (spartin)
Description:
Lipophagy receptor that plays an important role in lipid droplet (LD) turnover in motor neurons. Localizes to LDs and interacts with components of the autophagy machinery, such as MAP1LC3A/C proteins to deliver LDs to autophagosomes for degradation via lipophagy. Lipid transfer protein required for lipid droplet degradation, including by lipophagy. Can bind and transfer all lipid species found in lipid droplets, from phospholipids to triglycerides and sterol esters but the direction of lipid transfer by spartin and its cargos are unknown. May be implicated in endosomal trafficking, or microtubule dynamics, or both. Participates in cytokinesis.
Synonyms: KIAA0610; SPG20; TAHCCP1
Tractability: Antibody: its Gene Ontology location is reachable by antibodies, with medium confidence. PROTAC: UniProt records ubiquitination sites on it; ubiquitination databases record sites on it.
Gene: Protein-coding gene on chromosome 13 (36,301,638 to 36,370,215, reverse strand). Ensembl gene ENSG00000133104.
Subcellular location: Cytoplasm; Midbody; Lipid droplet
Subcellular location (Human Protein Atlas): Cytosol
Gene Ontology:
Molecular function: lipid binding; protein binding; ubiquitin protein ligase binding
Biological process: cell division; lipid transport; lipophagy; midbody abscission; regulation of mitochondrial membrane potential; negative regulation of BMP signaling pathway
Cellular component: cytoplasm; cytosol; lipid droplet; midbody; mitochondrial outer membrane; plasma membrane
Genetic constraint (gnomAD): Loss-of-function variants: 37 observed, 64.1 expected, observed/expected ratio (o/e) 0.58, 90% interval 0.44 to 0.76. The upper end of that interval is the gene's LOEUF score, 0.76, which puts it in group 3 of 6, group 1 being the genes least tolerant of losing a copy. Missense variants: 729 observed, 828.68 expected, observed/expected ratio (o/e) 0.88, 90% interval 0.83 to 0.94. Synonymous variants: 284 observed, 297.84 expected, observed/expected ratio (o/e) 0.95, 90% interval 0.87 to 1.05.
Gene-disease validity (ClinGen):
ClinGen rates the evidence that SPART causes each of these diseases.
Troyer syndrome (autosomal recessive): Definitive.
Homologues: Orthologues: chimpanzee SPART (99% identical), macaque SPART (99% identical), dog SPART (91% identical), rabbit SPART (90% identical), pig SPART (88% identical), mouse Spart (86% identical), guinea pig SPART (86% identical), rat Spart (85% identical), tropical clawed frog spart (54% identical), zebrafish spartb (51% identical), zebrafish sparta (39% identical), Drosophila melanogaster spartin (20% identical), and 1 more.
Diseases named in the same sentence as SPART in open-access papers:
SPART is named in the same sentence as 45 diseases in open-access papers, as found by Europe PMC text mining. Sharing a sentence is not in itself a finding about the gene and the disease. The quoted sentences say what the papers report.
Troyer syndrome (29 papers, 2004 to 2024). "This process involves spartin, mutations of which cause the rare inherited disorder Troyer syndrome (or spastic paraplegia-20, SPG20)." (PMID 38808280, 2024). "In humans, loss of spartin function due to SPART mutations leads to Troyer syndrome, a complex hereditary spastic paraplegia with degeneration of motor neurons." (PMID 37443287, 2023). "Pathogenic variants in SPART cause Troyer syndrome, characterized by lower extremity spasticity and weakness, short stature and cognitive impairment, and a severe mitochondrial impairment." (PMID 37433330, 2023). "Spastic paraplegia 20 (SPG20)/Spartin is mutated in Troyer syndrome, a neurological disorder characterized by distal amyotrophy." (PMID 38129384, 2023). "Troyer syndrome is caused by loss-of-function mutations in SPART, also known as SPG20, which encodes for Spartin, a multifunctional protein that consists of a N-terminal microtubule interacting and trafficking (MIT) domain and a C-terminal senescence domain." (PMID 37433330, 2023). "In summary, we were able to further elucidate the cellular role of Spartin and the pathological mechanisms related to loss of Spartin function in Troyer syndrome and to provide a possible therapeutic pathway for the affected individuals." (PMID 37433330, 2023). "SPG20 is known to be involved in Troyer syndrome, where its mutation leads to the downregulation of spartin expression." (PMID 35627246, 2022). "SPART is the pathogenic gene causing Troyer Syndrome, an extremely rare autosomal recessive disease that affects the nervous system, characterized by spastic paraplegia and distal amyotrophy." (PMID 34573300, 2021). "Troyer Syndrome, a complicated form of hereditary spastic paraplegias (HSPs), is caused by mutations in the gene coding for spartin (SPG20), resulting in a dysfunctional protein." (PMID 29234670, 2017). "Mutations in SPG20 lead to loss of function of the protein spartin, which results in Troyer Syndrome." (PMID 29234670, 2017). "For example, mutations in SPG20/Spartin (MIM 607111) are associated with Troyer syndrome, a complex form of hereditary spastic paraplegia (MIM 275900) characterized by short stature and cognitive deficits in addition to progressive ascending spasticity." (PMID 25077174, 2014). "Troyer syndrome is an autosomal recessive HSP caused by a frameshift mutation in the spartin (SPG20) gene." (PMID 21559443, 2011). "Troyer syndrome, a neurological disease, is associated with a truncated form of the ubiquitin ligase binding protein Spartin (also called SPG20)." (PMID 21203462, 2010). "The gene for the protein spartin was identified in the search for mutations causing a complicated form of HSP called Troyer syndrome." (PMID 20646264, 2010). "Previously, we demonstrated that this mutation results in a complete loss of spartin and postulated that Troyer syndrome has a loss-of-function disease mechanism." (PMID 20504295, 2010). "Troyer syndrome is an autosomal recessive HSP caused by a frameshift mutation in the spartin gene (SPG20), resulting in a loss of expression of the mutated protein." (PMID 20504295, 2010). "The same region is also weakly related (26% identity) to human Spartin, the product of the SPG20 gene mutated in Troyer syndrome, a form of “complicated” HSP." (PMID 15562320, 2004). "Additionally, SPART (spartin), mainly mediates the autophagic degradation of lipid droplets in neurons, the gene mutations of which can lead to Troyer syndrome, a form of complex hereditary spastic paraplegia." (PMID 38542126, 2024). "Spartin (SPG20) is mutated in Troyer syndrome, a complicated form of autosomal recessive HSP." (PMID 25875445, 2015). "A nucleotide deletion (1110delA) in spartin (SPG20) causes autosomal recessive Troyer syndrome." (PMID 20504295, 2010). "The gene encoding for the protein spartin causes a complicated form of HSP called Troyer syndrome (SPG20)." (PMID 34041268, 2021).
Troyer syndrome (continued). "Our identification of spartin as a lipophagy receptor, thus, suggests that impaired LD turnover contributes to Troyer syndrome development." (PMID 37443287, 2023). "Proteins such as spartin and seipin are involved in the lipid droplets’ biogenesis, and alterations in the gene lead to Troyer syndrome or SPG20 and SPG17." (PMID 35887006, 2022). "Spartin is a cytosolic protein that can be recruited to LDs upon treatment with oleic acid, via a C-terminal region that is deleted in Troyer syndrome mutants." (PMID 34041268, 2021). "Troyer syndrome, which is caused by homozygous mutations of the SPG20/spartin gene, is a prototypical complicated HSP with skeletal abnormalities including short stature, foot deformities, and kyphoscoliosis." (PMID 30029526, 2018). "Troyer syndrome is caused by a mutation in the SPG20 gene, which results in complete loss of expression of the protein spartin." (PMID 26114733, 2015). "Now, based on the SPAA pathway for lipid droplet turnover, we can begin unraveling the specific biological role of spartin in Troyer syndrome." (PMID 20504295, 2010). "Analysis of the specific role of spartin in neurons should yield a better understanding of the unexpected connection between lipid-droplet dynamics and neuronal degeneration as seen in Troyer syndrome." (PMID 20646264, 2010). "Since PLIN2 resides on LD membranes and regulates TAG turnover, spartin may play a role in LD regulation in cells and contribute to Troyer syndrome pathology." (PMID 32848541, 2020). "Spartin is a multi-functional unit that associates with LD, and a lack of spartin expression contributes to a HSP form called Troyer syndrome." (PMID 32848541, 2020). "In addition, spartin/SPG20, a protein mutated in the motor neuron disease known as the Troyer’s syndrome, is found on LDs and is implicated in LD turnover." (PMID 25826266, 2015). "The disease is caused by a frameshift mutation in the spartin gene (SPG20) resulting in a lack of expression of spartin rather than expression of a truncated protein, indicating that the pathogenesis of Troyer syndrome results from a loss-of-function mechanism." (PMID 21559443, 2011). "Interestingly, spartin's localization to lipid droplets depends on the carboxy-terminal part of the protein that is deleted in Troyer syndrome, which suggests that defects in lipid-droplet formation and dynamics in neurons could underlie this syndrome." (PMID 20646264, 2010). "Our findings suggest that spartin is an important player in the physiological function of mitochondria and that lack of spartin's expression in patients with Troyer syndrome might cause impaired mitochondrial calcium handling, which could contribute to the pathophysiology of the disease." (PMID 21559443, 2011). "To confirm these findings in another cellular model (i.e., lack of spartin's expression) of Troyer syndrome, we used neurons derived from Spg20 KO mice." (PMID 21559443, 2011). "Our previous studies found that in fibroblasts derived from patients with Troyer syndrome there is a lack of expression of truncated spartin protein, implying that the pathology of this disease occurs via a loss-of-function mechanism." (PMID 21559443, 2011). "It is reasonable to suggest that several cellular dysfunctions due to lack of spartin's expression contribute to a complex constellation of phenotypic symptoms present in patients with Troyer syndrome." (PMID 21559443, 2011). "Interestingly, in all three patients a specific diagnosis of Troyer syndrome (OMIM 275900, SPG20) was hypothesized during the course of the disease, but genetic tests for SPART (OMIM 607111, SPG20) were negative." (PMID 30381913, 2018).
colorectal cancer (10 papers, 2011 to 2025). A primary or metastatic malignant neoplasm that affects the colon or rectum. "Indeed, Galectin-3-binding protein (LGALS3BP), gelsolin (Gsn), and Spartin (Spg20), which are associated with a favorable clinical outcome in colorectal carcinoma are downregulated in APLN-expressing cells and upregulated in APLN-DM-expressing cells." (PMID 39962271, 2025). "The SPG20 gene encodes a protein called Spartin that has been found to be involved in intracellular epidermal growth factor receptor trafficking; SPG20 promoter has been found to be hypermethylated in colorectal cancer, resulting in gene silencing and cytokinesis arrest." (PMID 33499054, 2021).
gastric cancer (9 papers, 2017 to 2024). A primary or metastatic malignant neoplasm involving the stomach. "The medical relevance of spartin goes beyond neurodegeneration, since the epigenetic silencing via hypermethylation of SPG20 is associated with colorectal and gastric cancer." (PMID 29234670, 2017). "In another article published in 2018, it was shown that the hypermethylation of SPG20 could be used as a biomarker for gastric cancer screening and that the absence of the spartin expression could be used as a prognostic factor for gastric cancer patients." (PMID 35627246, 2022).
hereditary spastic paraplegia (8 papers, 2010 to 2025). Hereditary spastic paraplegias (HSP) comprise a genetically and clinically heterogeneous group of neurodegenerative disorders characterized by progressive spasticity and hyperreflexia of the lower limbs. "Hereditary spastic paraplegias, a group of neurodegenerative disorders, can be caused by loss-of-function mutations in the protein spartin." (PMID 29234670, 2017). "ITCH, such as WWP1, another NEDD4 E3, interacts with spartin, a protein encoded by the SPG20 gene which is mutated in an autosomal recessive form of hereditary spastic paraplegia." (PMID 35409239, 2022). "The current findings show, however, that the spartin-mediated lipophagy pathway may be particularly important in neurons given the connection of spartin with hereditary spastic paraplegia." (PMID 37443287, 2023).
Spastic paraplegia (8 papers, 2008 to 2023). Complete loss of the ability to move the lower limbs accompanied by spasticity of the lower limbs. "Mutation of the protein spartin is a cause of one form of spastic paraplegia." (PMID 20646264, 2010). "However, the wide spectrum of molecular defects due to mutant Spartin that result in spastic paraplegia is still partially unknown and Spartin precise role in regulating these cellular processes remains poorly understood." (PMID 37433330, 2023).
paraplegia (4 papers, 2014 to 2021). Complete paralysis of the lower half of the body including both legs, often caused by damage to the spinal cord. "Finally, Spartin, the Drosophila ortholog of the protein encoded by the spastic paraplegia gene SPG20 was Rab18 specific in both data sets, and we confirmed that this interaction was GTP dependent." (PMID 25453831, 2014). "Furthermore, anti-hnRNP A1-M9 antibodies transfected into human neuronal cells in vitro altered RNA levels of the spastic paraplegia genes (SPGs) spastin (SPG4), spartin (SPG20), and paraplegin (SPG7) as shown by microarray." (PMID 27375925, 2016).
developmental delay (3 papers, 2010 to 2023). "SPART biallelic missense variants were detected in a 5-year-old boy with short stature, developmental delay and muscle weakness with impaired walking distance." (PMID 37433330, 2023).
Parkinson disease (3 papers, 2009 to 2018). A progressive degenerative disorder of the central nervous system characterized by loss of dopamine producing neurons in the substantia nigra and the presence of Lewy bodies in the substantia nigra and locus coeruleus. "Grp78 (also known as HSPA5) is important for endoplasmic reticulum (ER) protein folding; it was found to play a neuroprotective role in a rat model of Parkinson disease and was also identified as a new binding partner of spartin, mutations in which can cause SPG20." (PMID 30061306, 2018). "For example, similar to spartin, wild-type and mutant A53T alpha-synuclein (which causes a dominant- negative form of Parkinson's disease), and protein kinase C (PKC) δ re-distribute from the cytoplasm to the lipid droplets after cells are treated with oleic acid." (PMID 21559443, 2011).
breast carcinoma (2 papers, 2019 to 2022). "KO of Spartin, or expression of the Spartin dominant-negative mutant, leads to accumulation of lipid droplets in breast cancer cells and mouse motor cortex neurons." (PMID 35646940, 2022).
neuroblastoma (1 paper, 2011). Neuroblastoma (NB) is the most common solid, extracranial childhood tumor. "Human neuroblastoma cells depleted of spartin and cortical neurons obtained from Spg20 KO mice showed depolarized mitochondrial membrane." (PMID 21559443, 2011). "We also found that knockdown of spartin by small interfering RNA in a human neuroblastoma cell line resulted in depolarization of the mitochondrial membrane." (PMID 21559443, 2011). "We examined the subcellular localization of endogenous spartin in the SK-N-SH neuroblastoma cell line by immunofluorescence using a recently developed polyclonal antibody against spartin." (PMID 21559443, 2011).
ovarian carcinoma (1 paper, 2022). A malignant neoplasm originating from the surface ovarian epithelium. "We also interrogated the 10 common genes identified by the RNAseq and proteomics and found that only the spartin (SPART) (KIAA0610) transcripts levels were significantly associated (* p < 0.05) with the PFS and OS of the ovarian cancer patients." (PMID 35008958, 2022).
senile osteoporosis (1 paper, 2026). "Overall, SPARTIN-mediated lipophagy is a critical metabolic regulator of MSC osteogenesis and represents a promising therapeutic target for senile osteoporosis." (PMID 42037167, 2026).
tumor (8 papers, 2018 to 2025). "The gene expression data showed a consistently higher expression of spartin in solid tissue normal compared to the tumor tissues (p < 0.001 by the Wilcoxon paired rank sum test)." (PMID 35627246, 2022). "The gene expression data showed a significantly higher expression of spartin in the normal counterparts when compared to the tumor samples (p < 0.001 by the Wilcoxon paired rank sum test)." (PMID 35627246, 2022). "The gene expression data confirmed the previous observations, since solid tissue normal expressed significantly higher spartin compared to their tumor counterpart (p < 0.001 by the Wilcoxon paired rank sum test)." (PMID 35627246, 2022). "The KIRP tumor samples displayed a lower spartin expression compared to their normal counterparts, whereas the KIRC tumor samples displayed higher levels compared to their normal counterparts." (PMID 35627246, 2022). "The gene expression data demonstrated, again, that the nontumor prostate expressed more spartin than the tumor counterpart, and this difference was statistically different (p < 0.001 by the Wilcoxon paired rank sum test)." (PMID 35627246, 2022).
SPART also shares sentences with these, for which no sentence is quoted: cancer (5 papers); adenoma (3); gastric tumors (3); neurological disorder (3); spinocerebellar ataxia (3); colon cancer (2); Distal amyotrophy (2); gastritis (2); Ataxia (1); autosomal dominant spastic paraplegia (1); autosomal dominant spastic paraplegia 3A (1); autosomal dominant spastic paraplegia 4 (1); Cerebellar atrophy (1); cognitive deficits (1); colorectal adenoma (1); diffuse large B-cell lymphoma (1); digestive system tumor (1); epilepsy (1); follicular lymphoma (1); frontotemporal dementia (1); hepatocellular carcinoma (1); infection (1); Kyphoscoliosis (1); mental disorder (1); motor neuron disease (1); multiple sclerosis (1); neurodegenerative disease (1); neutropenia (1); non-Hodgkin lymphoma (1); spinal muscular atrophy (1).
A further 2 diseases each share a sentence with SPART in 1 paper.